EBF3 (EBF transcription factor 3)
Description:
Transcriptional activator. Recognizes variations of the palindromic sequence 5'-ATTCCCNNGGGAATT-3' (By similarity).
Synonyms: EBF-3; O/E-2; OE-2; COE3; DKFZp667B0210; HADDS
Tractability: Small molecule: it has a high-quality binding pocket. PROTAC: ubiquitination databases record sites on it.
Gene: Protein-coding gene on chromosome 10 (129,835,233 to 129,973,053, reverse strand). Ensembl gene ENSG00000108001.
Subcellular location: Nucleus
Subcellular location (Human Protein Atlas): Nucleoplasm; Vesicles
Gene Ontology:
Molecular function: DNA-binding transcription factor activity, RNA polymerase II-specific; RNA polymerase II cis-regulatory region sequence-specific DNA binding; DNA binding; DNA-binding transcription factor activity
Biological process: positive regulation of DNA-templated transcription; regulation of transcription by RNA polymerase II; regulation of DNA-templated transcription
Cellular component: nucleus; chromatin
Genetic constraint (gnomAD): Loss-of-function variants: 16 observed, 68.8 expected, observed/expected ratio (o/e) 0.23, 90% interval 0.16 to 0.35. The upper end of that interval is the gene's LOEUF score, 0.35, which puts it in group 1 of 6, group 1 being the genes least tolerant of losing a copy. Missense variants: 543 observed, 784.62 expected, observed/expected ratio (o/e) 0.69, 90% interval 0.64 to 0.74. Synonymous variants: 344 observed, 320.75 expected, observed/expected ratio (o/e) 1.07, 90% interval 0.98 to 1.17.
Gene-disease validity (ClinGen):
ClinGen rates the evidence that EBF3 causes each of these diseases.
hypotonia, ataxia, and delayed development syndrome (autosomal dominant): Definitive.
Homologues: Orthologues: dog EBF3 (99% identical), pig EBF3 (99% identical), rat Ebf3 (97% identical), mouse Ebf3 (93% identical), chimpanzee EBF3 (93% identical), tropical clawed frog ebf3 (91% identical), guinea pig EBF3 (90% identical), macaque EBF3 (85% identical), zebrafish ebf3a (83% identical), rabbit EBF3 (78% identical), Drosophila melanogaster kn (56% identical), Caenorhabditis elegans unc-3 (46% identical). Paralogues in human: EBF1 (83% identical), EBF2 (75% identical), EBF4 (71% identical).
Diseases named in the same sentence as EBF3 in open-access papers:
EBF3 is named in the same sentence as 79 diseases in open-access papers, as found by Europe PMC text mining. Sharing a sentence is not in itself a finding about the gene and the disease. The quoted sentences say what the papers report.
Ataxia (16 papers, 2017 to 2025). Ataxia refers to impaired coordination of voluntary muscle movement. "EBF3 is a gene with an excess of protein-coding de novo variants and underlies Hypotonia, Ataxia, and Delayed Development Syndrome." (PMID 41081394, 2025). "This enhancer targets the gene EBF3 that is the underlying gene for Hypotonia, Ataxia, and Delayed Development Syndrome (HADDS)." (PMID 41081394, 2025). "Haploinsufficiency of EBF3 was reported by multiple groups to cause hypotonia, ataxia, and delayed development syndrome, but orofacial clefting was not reported as a consistent feature." (PMID 37532691, 2023). "Previous trio ESusing peripheral blood revealed a pathogenic heterozygous EBF3 missense variant in NM_001005463:c.488G > A p.(Arg163Gln), associated with hypotonia, ataxia and delayed development syndrome (MIM: 617,330)." (PMID 37798624, 2023). "Only a small number of human patients have been identified with rare de novo variants in EBF3 but these patients consistently displayed intellectual disability, ataxia, and facial dysmorphologies." (PMID 37532691, 2023). "EBF3 is a recently discovered gene associated with a syndromic form of NDDs characterized by hypotonia, ataxia and facial features." (PMID 36937983, 2023). "More specifically, EBF3 point mutations were reported to cause a condition named Hypotonia, Ataxia, and Delayed Development Syndrome (HADDS)." (PMID 34680908, 2021). "Mutations in Ebf3 disturb transcriptional profiles and cause intellectual disability, ataxia, and facial dysmorphism in humans." (PMID 29943428, 2018). "Early B-cell factor 3 (EBF3)-related syndrome, also known as hypotonia, ataxia, and delayed development syndrome (HADDS), is a recently recognized neurodevelopmental disorder frequently associated with bladder dysfunction." (PMID 39109108, 2024). "A pattern of CAS alongside dysarthria is not uncommon in other genetic forms of persistent speech disorder, for example in Koolen de Vries Syndrome, SETBP1-haploinsufficiency disorder, or EBF3-related core motor disturbance and ataxia." (PMID 36117209, 2023). "The core phenotypes include cerebellar ataxia, severe intellectual disability, subtle facial dysmorphism, strabismus, and vesicoureteric reflux, suggesting that EBF3 has a widespread developmental role." (PMID 35857265, 2022). "Individuals with DNVs in EBF3 had higher rates of ataxia compared to all individuals with DNVs in EBF3, while this phenotype was also absent in individuals with hs737 DNVs." (PMID 34256850, 2021). "Our analysis revealed this enhancer targets the transcription factor gene EBF3 which is enriched for coding DNVs in the hypotonia, ataxia, and delayed development syndrome (HADDS)." (PMID 34256850, 2021). "Deficits in EBF3 function result in hypotonia, ataxia and delayed development syndrome (HADDs)." (PMID 35857265, 2022). "Mutations in early B cell factor 3 (EBF3) were recently described in patients with a neurodevelopmental disorder (NDD) that includes developmental delay/intellectual disability, ataxia, hypotonia, speech impairment, strabismus, genitourinary abnormalities, and mild facial dysmorphisms." (PMID 29062322, 2017). "Patients with EBF3-related NDD mainly manifest DD/ID, ataxia, hypotonia, often accompanied by subtle facial features, strabismus, genitourinary abnormalities and structural abnormalities." (PMID 36937983, 2023).
Intellectual disability (11 papers, 2017 to 2025). "To test if the optimised dual-enSERT-2 can rapidly detect the quantitative effects of other disease-linked non-coding variants, we returned to the autism- and intellectual disability-linked hs737/EBF3 locus." (PMID 39762235, 2025). "Mutations in the gene early B cell factor 3 (EBF3) cause a neurodevelopmental disorder characterized mainly by intellectual disability and hypotonia." (PMID 40406967, 2025). "Within the EBF3 mutation group, there are significantly higher rates of intellectual disability or global developmental delay compared to the hs737 group (p = 0.00088) and we find significantly higher rates of autism within the hs737 DNV group when compared to the EBF3 group (p = 0.0088)." (PMID 34256850, 2021). "In addition, overexpression of Ln-CR1 greatly increase expression of Ebf3, a gene reported to be associated with Intellectual Disability." (PMID 33760820, 2021). "Previous studies delineate that haploinsufficiency of EBF3 is a critical contributor to developmental delay, intellectual disability, and particular facial dysmorphisms in patients bearing point mutations and indels in this gene." (PMID 34256807, 2021). "Also in mice, Ebf3 was shown to be a direct downstream target of the transcriptional repressor Arx, which itself is involved in a neurodevelopmental syndrome consisting of intellectual disability, seizures, and dystonia." (PMID 40406967, 2025). "All individuals with a coding DNV in EBF3 regardless of position within the protein presented with an intellectual disability or global developmental delay, while no individuals with a DNV in hs737 had either of these phenotypes." (PMID 34256850, 2021).
melanoma (9 papers, 2017 to 2025). A malignant, usually aggressive tumor composed of atypical, neoplastic melanocytes. "Subsequent data revealed that EBF3 promoter methylation causes elevated EBF3 expression, which leads to metastatic characteristics in melanoma cells." (PMID 35740696, 2022). "When melanoma cell lines were treated with a demethylating agent, decitabine, reduction in EBF3 gene expression was associated with demethylation of the EBF3 promoter DMF, supporting the notion that reducing methylation of the EBF3 promoter causes reduction of the corresponding EBF3 mRNA levels." (PMID 28030832, 2017). "EBF3 promoter hypermethylation in the metastatic melanoma cell lines was unexpectedly associated with elevated (rather than decreased) EBF3 expression, and this was also observed in melanoma patients in the TCGA database." (PMID 28030832, 2017). "EBF3 is a putative epigenetic driver of melanoma metastasis, which exhibits the paradoxical activation of transcription with a hypermethylated promoter." (PMID 40307913, 2025). "Using the SuperNova TAGging (SunTag) system, highly efficacious manipulation of DNA methylation of the EBF3 gene was shown in multiple melanoma cell lines." (PMID 40307913, 2025). "Previous editing of our target EBF3 locus using a dCas9-SunTag-scFvDNMT3A/TET1CD system was able to induce notable methylation changes in three melanoma cell lines." (PMID 38473261, 2024). "A prior study involving melanoma cell lines demonstrated a decrease in the expression of the EBF3 gene upon decitabine (DNA methylating inhibitor) treatment." (PMID 38473261, 2024). "Further research is needed to explore how the activation of EBF3 affects the IFN pathway in melanoma, potentially offering new insights into immune-mediated mechanisms in cancer progression and treatment strategies." (PMID 38473261, 2024). "The study employs a CRISPR-SunTag All-in-one system to manipulate the DNA methylation of the EBF3 gene promoter segment in melanoma cells." (PMID 38473261, 2024). "Contrary to earlier findings, we identified EBF3 as a putative epigenetic driver of metastasis in melanoma and other cancer types, displaying the phenomenon of hypermethylation causing gene activation." (PMID 38473261, 2024). "Here, we focused on editing the DNA methylation of a specific gene promoter segment (EBF3) in melanoma cells using the All-in-one system." (PMID 38473261, 2024). "Previously, we extensively analysed EBF3 methylation levels in melanoma and other cancers and identified EBF3 as a putative epigenetic driver of cancer metastasis, particularly in melanoma." (PMID 38473261, 2024). "Previous studies using RRBS or WGBS in melanoma cell lines described that methylation differences between primary and metastatic melanomas at TBC1D16 and EBF3 were associated with tumor progression." (PMID 38203489, 2023). "We identified the EBF3 gene as a putative epigenetic driver of melanoma metastasis and in several other solid cancers, which shows the paradoxical activation of transcription from a highly methylated promoter." (PMID 34771597, 2021). "Taken altogether, these results suggest that the EBF3 promoter hypermethylation and gene body hypomethylation is associated with tumour progression and metastasis, and it might be a characteristic aggressive change shared by both melanoma and colorectal cancer." (PMID 31383000, 2019). "EBF3 promoter hypermethylation and corresponding gene expression were positively correlated in TCGA melanoma samples (P-value = 0.025, Spearman's rank correlation)." (PMID 28030832, 2017). "Analysis of TCGA data suggested that EBF3 was relatively highly expressed in a subgroup of metastatic melanomas as compared to primary melanomas." (PMID 28030832, 2017). "In this cohort EBF3 promoter methylation in metastatic melanomas (median = 0.22) was significantly greater than promoter methylation of primary melanomas or normal melanocytes (median= 0.08 and 0.06 respectively, P-value = 0.0004, Mann Whitney U test)." (PMID 28030832, 2017).
melanoma (continued). "The results confirmed the EBF3 promoter DMF hypermethylation in the metastatic melanoma cell lines, and we observed excellent concordance for the DMF methylation between RRBS and the bisulfite sequencing (Pearson's r = 0.998, P-value = 0.002)." (PMID 28030832, 2017). "From the present RRBS analysis of paired primary and metastatic melanoma cell lines, EBF3 was identified as a candidate oncogenic metastasis epi-driver." (PMID 28030832, 2017). "Furthermore, we have effectively demonstrated the paradoxical relationship between EBF3 gene expression and DNA methylation in melanoma cell lines." (PMID 38473261, 2024). "Thus, EBF3 in the context of melanoma presents a favourable framework to establish the mechanism of paradoxical gene expression." (PMID 38473261, 2024). "Using transient system delivery, we demonstrate both highly efficacious methylation and demethylation of the EBF3 promoter, which is a putative epigenetic driver of melanoma metastasis, achieving up to a 304.00% gain of methylation and 99.99% relative demethylation, respectively." (PMID 34771597, 2021). "Furthermore, we demonstrate highly efficacious methylation and demethylation of the EBF3 promoter across a panel of melanoma cell lines." (PMID 34771597, 2021). "Therefore, we next decided to investigate the functional role of EBF3 as a potential driver of melanoma metastasis." (PMID 28030832, 2017). "To determine whether the cell line expression data was reflected in the findings from melanoma patient samples, we compared EBF3 mRNA expression in primary and metastatic patients from TCGA RNA-Seq data." (PMID 28030832, 2017). "We next determined whether EBF3 knockdown affects melanoma cell migration and invasion using Boyden Chamber assays, with or without a Matrigel membrane coating, to investigate invasion and migration, respectively." (PMID 28030832, 2017). "Mirroring the cell lines, significantly higher expression of EBF3 mRNA (P-value = 7.427e–05, Mann Whitney U test) was observed in metastatic tumors (median normalized count = 31.63, mean count = 156) compared to primary melanomas (median normalized count = 17.87, mean = 55.16)." (PMID 28030832, 2017). "An adjacent EBF3 promoter region, approximately 200–300 bp upstream from the region identified by RRBS, was investigated in TCGA melanoma data, and was also found to exhibit high levels of DNA methylation." (PMID 28030832, 2017). "Thus, to assess whether targeted methylation editing at the EBF3 locus impacts the local chromatin-associated histone modifications, we performed Cleavage Under Targets and Release Using Nuclease (CUT and RUN) assays on the baseline, unedited, and edited melanoma cell lines." (PMID 38473261, 2024). "For instance, high levels of promoter methylation correlated with active expression of EBF3, MGMT, HOXD12 and GATA4 in melanoma, indicating other factors may affect the relations of DNA methylation with transcriptional activity." (PMID 34013637, 2021). "This was expected as our data show that the EBF3 promoter was already unmethylated in these cells, and suggests that the reduction of EBF3 mRNA levels in the melanoma cell lines is less likely to be a non-specific effect." (PMID 28030832, 2017). "One gene, Early B Cell Factor 3 (EBF3), exhibited promoter hypermethylation in metastatic cell lines, and was validated with bisulfite sequencing and in two publicly available independent melanoma cohorts (n = 40 and 458 melanomas, respectively)." (PMID 28030832, 2017).
developmental delay (6 papers, 2017 to 2023). "They all covered the EBF3 gene, which was of autosomal dominant inheritance and associated with developmental delay in OMIM." (PMID 36937983, 2023). "Upon validation via trio whole-exome sequencing and Sanger sequencing, we report a novel heterozygous missense mutation, c.589A > G, in EBF3 in a boy with global developmental delay." (PMID 34367240, 2021). "Variants in EBF3, which encode for the early B Cell Factor 3, may contribute to developmental delay and intellectual impairment." (PMID 31004082, 2019).
autism (5 papers, 2021 to 2025). Persistent deficits in social interaction and communication and interaction as well as a markedly restricted repertoire of activity and interest as well as repetitive patterns of behavior. "While features of autism are present in only a subset of those with EBF3 coding mutations, noncoding de novo variants in an EBF3 enhancer were found in families with autism." (PMID 40406967, 2025). "Chromatin binding genes account for a sizeable fraction of DNM attributable cases of autism, suggesting that EBF3 disruption could result in a milder phenotype in the spectrum, as we observe in these cases." (PMID 34256850, 2021). "For example, we identified transcripts of candidate genes for autism not expressed in the brain (Pax5) or specifically absent in brainstem (Arx, Foxg2) or striatum (Ebf3)." (PMID 39920851, 2025). "EBF3 is a well-established NDD gene with genome-wide significant enrichment of coding DNVs and an established syndrome called HADDS that shares the phenotype of hypotonia with the individuals with autism in our study that had hs737 noncoding DNVs." (PMID 34256850, 2021).
breast carcinoma (4 papers, 2011 to 2025). "Meanwhile, another Team Ang Zheng found that SNORA47 affected stemness and chemotherapy sensitivity of Luminal breast cancer cells via EBF3/RPL11/c-Myc axis, providing a new direction for precision therapy of Luminal breast cancer patients." (PMID 40567603, 2025). "However, the changes in the expression of RPL11 in the nucleolus and nucleoplasm persisted after overexpression of EBF3 in SNORA47-silenced-expressing breast cancer cells." (PMID 40264043, 2025). "EBF3 in breast cancer cells should be further explored in the future." (PMID 40264043, 2025). "Therefore, SNORA47 affected the stemness phenotype of breast cancer cells by influencing the interactions between EBF3 and RPL11, which consequently influenced the stemness phenotype and sensitivity of the breast cancer cells." (PMID 40264043, 2025). "In contrast to the vector control group, the effective knockdown of EBF3 markedly suppressed the upregulated expression of Nanog, OCT4 and SOX2 in MCF-7 and T47D breast cancer cells that exhibited overexpression of SNORA47." (PMID 40264043, 2025). "The purpose of this research is to elucidate the intricate molecular interactions among SNORA47, EBF3, and RPL11 in breast cancer cells." (PMID 40264043, 2025). "Additionally, our study revealed an interaction between EBF3 and RPL11 in breast cancer cells through Co-IP analysis." (PMID 40264043, 2025). "Furthermore, silencing EBF3 in SNORA47-overexpressing breast cancer cells resulted in the disappearance of changes in c-Myc expression, whereas overexpression of EBF3 did not alter the effect of SNORA47 knockdown on c-Myc expression in breast cancer cells." (PMID 40264043, 2025). "For example, no clear overall pattern of EBF3 methylation patterns was identified between a paired breast cancer primary and metastases, although some individual sites showed differences (e.g. the CpG site at chr10:131763531 was 46% less methylated in metastasis)." (PMID 31383000, 2019).
head and neck squamous cell carcinoma (3 papers, 2012 to 2019). A squamous cell carcinoma that arises from any of the following anatomic sites: lip and oral cavity, nasal cavity, paranasal sinuses, pharynx, larynx, and salivary glands. "In contrary, the overexpression of SLC5A8 together with IRX1 and EBF3 may be involved in the transforming growth factor beta signaling pathway, which is often disrupted in head and neck squamous cell carcinoma." (PMID 31754358, 2019).